HOTAIR (HOX transcript antisense RNA)
Diseases named in the same sentence as HOTAIR in open-access papers (continued):
Sharing a sentence is not in itself a finding about the gene and the disease.
cancer (continued). "In humans, increased HOTAIR expression is associated with promotion of cancer metastasis, where it has been shown to reprogram the cellular chromatin state by re-targeting Polycomb Repressive Complex 2 (PRC2)." (PMID 29137239, 2017). "The enrolled SNPs and cases including patients and controls in our study are also much more than those in any study, implying that our assessment of the relationship between the HOTAIR gene SNPs and cancer risk is relatively more precise." (PMID 27965458, 2017). "In summary, our meta-analysis implicates possible relationship between HOTAIR polymorphisms and cancer risk in Chinese population." (PMID 28938673, 2017). "In 2016, three similar meta-analyses involving eight articles explored the association of HOTAIR polymorphisms with several kinds of cancers among worldwide population." (PMID 28938673, 2017). "In conclusion, HOTAIR SNP rs920778, rs7958904 and rs874945 are cancer risk factors, among of which rs920778 is also useful in evaluating cancer risk of Asian population and digestive cancer." (PMID 27965458, 2017). "The function of HOTAIR in regulation of chromosome occupancy which in turn enforces a silent chromatin state at Hox gene and other additional genes associated with cancer development and metastasis." (PMID 28039476, 2017). "We performed a meta-analysis to clarify the association between the expression of HOTAIR and the clinicopathological features and prognosis in different cancers." (PMID 28591050, 2017). "Overall, our results demonstrated that rs920778 polymorphism of HOTAIR was significantly associated with increased cancer risk among Chinese population." (PMID 28938673, 2017). "Given its important roles, it is unsurprising that the deregulation of HOTAIR has been implicated in various types of human cancer." (PMID 28649178, 2017). "Some previously reported cancer-associated lncRNAs, such as HOTAIR, UCA1, and MALAT1, were found to be differentially expressed in our study, but none was in our top, validated list." (PMID 28415559, 2017). "Although HOTAIR polymorphisms are associated with assessment of cancer risk, abnormal expression of HOTAIR itself is also useful in predicting cancer prognosis." (PMID 27965458, 2017). "In these 38 included articles, we observed that a variety of lncRNA genes had been investigated the association with cancer risk, among which lncRNA HOTAIR, PRNCR1, H19, and POLR2E had been widely studied." (PMID 28159929, 2017). "Long non-coding RNAs (lncRNAs) have also been increasingly implicated in tumor biology, yet beyond studies of previously cancer-associated transcripts such as HOTAIR, MALAT-1, and NEAT-1, their significance in HNSCC is sparsely characterized." (PMID 27323410, 2016). "As a cancer-associated lncRNA, HOTAIR is a prospective biomarker of metastasis and poor prognosis in a diverse group of cancers." (PMID 27686732, 2016). "Previously, studies have investigated the association between HOTAIR variants and several cancers, such as breast cancer, gastric cancer, colorectal cancer, esophageal squamous cell carcinoma, and gastric cardia adenocarcinoma." (PMID 26967389, 2016). "Here, a meta-analysis was performed to derive a more precise estimation of the involvement of HOTAIR polymorphisms in cancer development." (PMID 27246974, 2016). "Here, a meta-analysis of eligible studies conducted before January 20, 2016 was performed in order to obtain more precise and comprehensive insight into the impact of HOTAIR polymorphisms on cancer susceptibility." (PMID 27246974, 2016). "Recently, another important mission of HOTAIR was uncovered that targeting HOTAIR caused cancer cell apoptosis." (PMID 26962687, 2016). "Through direct interaction with histone modification complexes, HOTAIR suppresses its target genes, and overexpression of HOTAIR is strongly associated with cancer metastasis and poor prognosis." (PMID 27215978, 2016).
cancer (continued). "The authors found that HOTAIR expression was associated with a poorer prognosis in patients with different types of cancer, as well as advanced pathological stage." (PMID 27148353, 2016). "We performed a meta-analysis using data from available cases (n = 7,772) and controls (n = 9,075) in the literature to date to provide further evidence that HOTAIR polymorphisms rs4759314 and rs920778 are associated with cancer risk." (PMID 27246974, 2016). "Recently, several studies have been performed to examine the possible link between polymorphisms in HOTAIR and cancer risk; however, the results have been inconclusive." (PMID 27010768, 2016). "Functional and clinical studies in a variety of cancers have correlated the loss of lncRNA HOTAIR regulation with carcinogenesis and metastasis." (PMID 27659532, 2016). "The results indicated that HOTAIR polymorphisms are associated with increased cancer risk, but mainly in stratified analysis based on ethnicity and cancer type." (PMID 27246974, 2016). "Our results included some well-known cancer-associated lncRNAs such as HOTAIR, PCA3, PCAT1, and CRNDE." (PMID 27147563, 2016). "All of these results confirmed the previous notion that HOTAIR deficiency led to cancer cell apoptosis." (PMID 26962687, 2016). "Nevertheless, the relationships of HOTAIR polymorphisms with cancer sensitivities have attracted much interest; however, the results are controversial." (PMID 27010768, 2016). "It is worth noting that HOTAIR is associated with motility, invasion, and metastatic potential of cancer." (PMID 26172293, 2015). "Elevated HOTAIR levels in particular have been reported in several cancers, and have been linked to metastasis and poor prognosis due to its regulatory role in invasive and proliferative phenotypes." (PMID 26404381, 2015). "An increasing number of studies have shown that the expression of HOTAIR is closely associated with a variety of cancers, suggesting that it is a cancer-associated lncRNA." (PMID 26307974, 2015). "HOTAIR is frequently up-regulated in different cancer tissues, in particular in aggressive forms, and associated with metastasis development and poor clinical outcome." (PMID 26580594, 2015). "We correlated the cross-cancer alteration of HOTAIR through either mutation, deletion, amplification with a broad number of cancer types." (PMID 25275300, 2014). "We found that HOTAIR expression was associated with a poorer prognosis in patients with different types of cancer." (PMID 25157956, 2014). "A significant association was observed between high HOTAIR expression and poor overall survival (OS) in patients with cancer (pooled HR 2.22, 95% CI: 1.68–2.93)." (PMID 25157956, 2014). "HOTAIR has been shown to contribute to the progression of many types of cancer and is nowadays considered as a hallmark of cancer." (PMID 25303230, 2014). "In this review, we will focus on the characteristics of HOTAIR, as well as data pertaining to its mechanism and its association with cancers." (PMID 25334066, 2014). "HOTAIR is negative prognostic factor for a variety of carcinomas, and HOTAIR expression levels are correlated with tumor metastases while loss of HOTAIR has been linked with decrease in cancer invasiveness." (PMID 24953832, 2014). "One emerging mechanism underlying up-regulation of HOTAIR in cancer cells is direct transcriptional activation of HOTAIR by classical oncogenes." (PMID 25491133, 2014). "In this review, we summarize recent research on HOTAIR lncRNA, with a focus on its identification, characterization, mechanism of action, and association with related human cancers." (PMID 25334066, 2014). "HOTAIR has been implicated in cancer invasion and metastasis through its role in chromatin remodeling." (PMID 25157956, 2014). "HOTAIR was one of the first metastasis-associated lncRNAs, described to have a fundamental role in cancer." (PMID 22613733, 2012).
cancer (continued). "Loss of HOTAIR impairs cancer cell invasiveness, whereas ectopic expression of HOTAIR relocalises PRC2 complex to bind to the target genes that are signified in embryonic fibroblasts." (PMID 22187039, 2012). "For example, personalized medicine could be designed to combat the lncRNA HOTAIR, which is upregulated in malignancies and associated with a bad prognosis, thereby making the cancer more sensitive to cuproptosis." (PMID 41335135, 2025). "This study examined the association of the HOTAIR rs920778 C > T polymorphism with cancer risk." (PMID 40642606, 2025). "Similarly, the lncRNA HOX transcript antisense RNA (HOTAIR), which is characterized by its role in chromatin remodeling and cancer progression, has also been linked to lipid metabolism." (PMID 40801625, 2025). "We identified HOTAIR as the lncRNA associated with all three cancer types." (PMID 40001977, 2025). "The rs920778 polymorphism may affect the expression of HOTAIR, thereby altering cancer-related pathways." (PMID 40642606, 2025). "We also analyzed the expression of genes involved in epigenetic factors, such as EZH2 (Enhancer of zest homolog 2), involved in histone modifications, and HOTAIR (a long non-coding RNA), two genes that have been associated with tumorigenesis in several cancers." (PMID 40868070, 2025). "HOX transcript antisense intergenic RNA (HOTAIR) is another lncRNA frequently overexpressed in numerous cancers, including OSCC, where its high levels are associated with advanced stage, metastasis, poor prognosis, and the promotion of epithelial-mesenchymal transition (EMT)." (PMID 41221298, 2025). "lncRNA HOTAIR has been associated with treatment resistance in various types of cancers." (PMID 38506091, 2024). "According to a publication, overexpression of HOTAIR may encourage the growth of cancer cells in tissues by causing metastasis to spread to additional sites and organs." (PMID 38294554, 2024). "Variations in HOTAIR expression, both downregulation and upregulation, have been observed in diverse cancer types, and single nucleotide polymorphisms (SNPs) located in the HOTAIR encoding gene have been recently associated with several multifactorial diseases." (PMID 38958113, 2024). "Such functions have made lncRNAs central players in the development and progression of numerous diseases, including cancer, where specific lncRNAs like HOTAIR, MALAT1, and HOTAIR have been linked to metastasis, highlighting their potential as therapeutic targets and biomarkers." (PMID 39325172, 2024). "In addition, cancer cells with high PRC2 expression became less aggressive due to HOTAIR deficiency." (PMID 37007957, 2023). "Additionally, genetic polymorphism in HOTAIR is linked with the risk and susceptibility of human cancer." (PMID 36980864, 2023). "Overall, the potential of HOTAIR as a metastatic, drug-resistant, and prognostic regulator highlights the importance of understanding the molecular mechanisms underlying cancer progression and identifying novel therapeutic targets for cancer treatment." (PMID 36997931, 2023). "Furthermore, high expression of HOTAIR is associated with drug resistance and poor overall survival (OS) in many cancers." (PMID 36924407, 2023). "Furthermore, HOTAIR has also been associated with poor prognosis and advanced tumor stage in cancers." (PMID 36273585, 2022). "In addition, several studies have implicated an oncogenic role for HOTAIR in the proliferation and metastasis of various cancers." (PMID 35087108, 2022). "Liu et al16 reported that in a meta-analysis of 17 of 116 studies including a total of 17 048 subjects, some polymorphisms including rs1899663 in HOTAIR play a role in genetic predisposition to other cancers in recessive and homozygote models in the Asian population." (PMID 35946893, 2022).
cancer (continued). "For example, HOTAIR, as a carcinogenic lncRNA, is highly expressed in breast cancer, gallbladder cancer and other cancers, is associated with invasion and metastasis and is a diagnostic and prognostic indicator for various cancers." (PMID 33764367, 2021). "Moreover, HOTAIR is overexpressed in several types of cancer; in these pathological states, HOTAIR can be associated with the induction of metastasis, anticancer drug resistance, and epithelial–mesenchymal transition." (PMID 34298896, 2021). "The long-stranded non-coding RNA HOTAIR is highly expressed and associated with metastasis in a variety of cancer types and promotes tumor metastasis at least in part through association with the PRC2 complex that induces redirection to hundreds of genes involved in tumor metastasis." (PMID 34887871, 2021). "In addition, a SNP located within the intronic region of HOTAIR has been shown to alter the binding affinity of the lncRNA to transcription factors associated with cancer including PAX-4, SOX, SPZ1 and ZFP281." (PMID 33499210, 2021). "HOTAIR, a cell cycle‐associated lncRNA, is linked to a range of major diseases, including cancer." (PMID 34180119, 2021). "The pooled results of a meta-analysis showed the rs7958904 polymorphism of HOTAIR significantly decreased susceptibility to overall cancer risk among five genetic models, while the rs920778 and the rs12826786 polymorphisms increased susceptibility to cancer risk in all genetic models." (PMID 34582651, 2021). "HOTAIR overexpression, for example, has been associated with an increase of metastasis, invasiveness, and, consequently, to poor outcomes in breast and other types of cancer." (PMID 33194754, 2020). "Furthermore, we found that some lncRNAs including HOTAIR and H19 were associated with poor survival across multiple cancer types." (PMID 32231885, 2020). "It is known that HOTAIR is also associated with an aberrant DNA methylation profile in cancer." (PMID 32397382, 2020). "Owing to the fact that cancer stemness was tightly associated with cancer metastasis, we sought to examine whether HOTAIR was a causal factor determining cancer stemnness." (PMID 32657763, 2020). "Functional studies through studies on statistically related polymorphisms may be a way to confirm the contribution of HOTAIR regulation in cancer onset/metastasis and maybe a major guideline for cancer onset and prognosis." (PMID 32117729, 2020). "Aberrant HOTAIR expression may dysregulate several genes associated with cancer development, and therefore promote the initiation, growth, and invasiveness of tumors." (PMID 32785167, 2020). "Although previous studies have indicated that HOTAIR rs4759314 and rs920778 polymorphisms can affect the expression of HOTAIR in different cancer types, we cannot validate the association between genetic variants of HOTAIR with expression level of HOTAIR in UCC." (PMID 30813594, 2019). "However, the association between these SNPs and regulation/structure of HOTAIR has to be checked in various cancers." (PMID 30873206, 2019). "Later, another investigation, published in the journal of “Cancer Biomarkers” on May 2018, also suggested positive association of circulating HOTAIR expression with tumour size, positive lymph node quantity and farther metastasis location." (PMID 31796041, 2019). "A recent study has indicated that lncRNA interactions with miRNA and mRNA—such as H19, MALAT1, and KCNQ1OT1, HULC, and HOTAIR—could be potential diagnostic and prognostic biomarkers in cancer." (PMID 31164794, 2019). "HOTAIR exhibits pro-oncogenic activity since it has been shown to be overexpressed in numerous cancers and be implicated in several hallmarks of cancer, such as cellular proliferation, inhibition of apoptosis, genomic instability, angiogenesis, invasion, and metastasis." (PMID 31195674, 2019).
cancer (continued). "Besides HOX transcription factors, HOX transcript antisense RNA (HOTAIR) also plays a regulatory role in autophagy and is associated with the invasion and metastasis capacities of several types of cancers." (PMID 31013831, 2019). "The lncRNA HOTAIR has been implicated in several human cancers." (PMID 29644006, 2018). "The MMP–HOTAIR axis can be associated with the role of HOTAIR in cancer progression." (PMID 29469819, 2017). "Collectively, our data demonstrated that HOTAIR-mediated cancer stemness and metastasis are associated with the regulation of EMT and HOTAIR may serve as a therapeutic target in OSCC." (PMID 29228709, 2017). "Interestingly, in recent two years, there have nine studies to investigate the association between HOTAIR polymorphisms and cancer risk." (PMID 28159929, 2017). "Recently, several studies have summarized the associations of HOTAIR SNPs with cancer risk." (PMID 27965458, 2017). "The opposite effect of rs7958904 on cancer risk may reflect the complex function of HOTAIR and its genetic variation is complex and depends on cell-type context." (PMID 28600545, 2017). "For instance, functional SNP rs4759314 in HOTAIR gene could affect the expression of HOTAIR, and upregulation of HOTAIR was significantly associated with development, progression, and prognosis of various cancers." (PMID 28818070, 2017). "Therefore, it is necessary to summarize all eligible individual studies and conduct a comprehensive meta-analysis to determine the correlations of HOTAIR polymorphisms with cancer susceptibility in Chinese population." (PMID 28938673, 2017). "The findings of our study provided evidence that HOTAIR polymorphisms might modify cancer susceptibility." (PMID 27010768, 2016). "Additionally, relationships of HOTAIR polymorphisms (including rs4759314 and rs920778) with the expression of HOTAIR and various cancer risks have been observed." (PMID 27010768, 2016). "In summary, except for the role of promoting metastasis and predicting bad prognosis, HOTAIR is vital for cancer cell survival and its knockdown causes cancer cell apoptosis; therefore targeting HOTAIR might be promising in cancer therapy." (PMID 26962687, 2016). "Furthermore, many other established, cancer-linked lncRNAs, including HOTAIR, MALAT-1, NEAT-1, and UCA-1, were found to be either extremely lowly expressed (mean and median cpm < 1) or insufficiently dysregulated in HNSCCs." (PMID 27323410, 2016). "Conclusively, understanding the biological roles of HOTAIR in different cancer types may help us to recruit this lncRNA as a diagnostic or predictive biomarker." (PMID 26967389, 2016). "Therefore, based on all of the currently published data, we performed a meta-analysis to more precisely characterize the associations of HOTAIR polymorphisms (rs920778, rs4759314 and rs1899663) with cancer risk." (PMID 27010768, 2016). "The strength of this meta-analysis is that we systemically reviewed the relationships between HOTAIR polymorphisms and tumour susceptibility for the first time, and we identified different associations of the rs920778 SNP with cancer risk in different ethnic populations." (PMID 27010768, 2016). "Recently, an increasing number of studies have investigated the associations of different HOTAIR expression levels with cancer survival, but fewer studies have focused specific attention on the relationships of HOTAIR polymorphisms with cancer susceptibility and survival." (PMID 27010768, 2016). "Therefore, we performed a meta-analysis to estimate the associations between HOTAIR polymorphisms (rs920778, rs4759314 and rs1899663) and cancer risk." (PMID 27010768, 2016). "This meta-analysis provided evidence that HOTAIR rs920778 may modify the susceptibility to certain cancer types." (PMID 27010768, 2016). "Here, HOTAIR was investigated for potential links to cancer susceptibility." (PMID 27246974, 2016).